PCDH8P1 (protocadherin 8 pseudogene 1)
Gene: Transcribed processed pseudogene on chromosome 13 (53,199,981 to 53,202,753, forward strand). Ensembl gene ENSG00000225510.
Diseases named in the same sentence as PCDH8P1 in open-access papers:
PCDH8P1 is named in the same sentence as 1 disease in open-access papers, as found by Europe PMC text mining. Sharing a sentence is not in itself a finding about the gene and the disease. The quoted sentences say what the papers report.
cancer (1 paper, 2022). A tumor composed of atypical neoplastic, often pleomorphic cells that invade other tissues. "The strongest association signal for PTSD was found on chromosome 13 (P = 4.79 × 10–20), in a region spanning noncoding mRNAs LINC01065, PCDH8P1, and RN7SL618P as well as olfactomedin 4–encoding gene OLFM4, which takes part in innate immunity, inflammation, and cancer." (PMID 33905376, 2022).